INS (insulin)
Diseases named in the same sentence as INS in open-access papers (continued):
Sharing a sentence is not in itself a finding about the gene and the disease.
diabetes (continued). "Both diabetes duration and the need for exogenous insulin (i.e., reflective of the loss of beta-cell function) can be indicators of progression of T2DM." (PMID 32903679, 2020). "Diabetes is an important risk predictor, particularly for insulin‐treated patients, as are having a second prior MI, a prior major bleed, peripheral arterial disease, and prior heart failure." (PMID 31713893, 2020). "Cluster 2 corresponds to severe insulin deficient diabetes with low fasting c-peptides and high HbA1c." (PMID 32182790, 2020). "Vitamin D deficiency is associated with abnormal placentation, altered angiogenesis, immune dysfunction, abnormal insulin secretion and action, adverse lipid profiles, and inflammation: problems that are also associated with diabetes." (PMID 32664257, 2020). "In summary, this study provides evidence that a strategy of treating patients with obesity and T2DM-Ins with SG or RYGB is associated with a significant incidence of diabetes remission and a high incidence of cessation of insulin therapy." (PMID 33285553, 2020). "Iatrogenic hypoglycemia is common in patients using insulin for diabetes and is a major cause of emergency department admissions and adverse CNS effects in older patients." (PMID 32513828, 2020). "As exemplified by the occurrence of diabetes in carriers of mutations affecting insulin production, any deficit along this supply chain can deplete beta cells of new insulin granule stores, thereby hampering their competence for glucose-stimulated secretion." (PMID 32894308, 2020). "Methotrexate (MTX) also reduces glycosylated haemoglobin (HbA1c) levels and the risk for diabetes in patients with RA, likely independently of insulin sensitivity." (PMID 32907617, 2020). "It has been reported that PPARγ mRNA and protein levels are downregulated by fasting and insulin-deficient diabetes." (PMID 32847136, 2020). "Insulin resistance, i.e., reduction in cellular responsiveness to insulin, is closely associated with other features of MetS, including diabetes and dyslipidemia." (PMID 33139628, 2020). "T2DM is the most prevalent type of DM which accounts for about 90-95% of patients with diabetes and is mainly linked to inadequate response to insulin (reduced insulin sensitivity) and insulin resistance in peripheral tissues." (PMID 32215179, 2020). "Acetate administration was also shown to reduce the size of intracellular lipid droplets in the same rat model of diabetes, and the authors propose that acetate levels act, in general, to counter the effects of reduced insulin and associated fat accumulation." (PMID 33304273, 2020). "Increased HOMA2-%B values are indicative of increased basal insulin secretion which is a type of beta cell dysfunction associated to diabetes development." (PMID 32042314, 2020). "β-cell function, glucose metabolism, insulin activity, and pathogenesis of diabetes are directly linked to zinc homeostasis." (PMID 32987721, 2020). "There is also an association between tau and diabetes, since both insulin and IGF-1 are involved in tau phosphorylation, which is associated with neurofibrillary tangles production and synaptic loss." (PMID 32872672, 2020). "In short, the autoimmune process is associated with diabetes, but that risk is a continuum, just as glucose and glucose disposition, insulin secretion and insulin sensitivity represent continua." (PMID 31813006, 2020). "Nine participants (17%) reporting diabetes reported regular insulin restriction for the purpose of weight loss (frequency of ≥1 per week)." (PMID 32128205, 2020). "Pancreatic β-cell apoptosis inevitably causes insufficient insulin, which is a vital factor in the initiation and progress of diabetes." (PMID 32970961, 2020). "The connection between abnormal insulin signaling and heart disease has already been reported, in that diabetes mellitus significantly increased the risk of ischemic heart disease." (PMID 32581823, 2020).
diabetes (continued). "Among a subgroup of population with insulin data (n = 803) those with insulin resistance (IR) that converted to diabetes showed a higher risk for CVD, 3.68 [(1.49–9.06), P = 0.01] and CHD, 2.76 [(1.00–7.60), P = 0.05] events in the fully adjusted model." (PMID 32228577, 2020). "High baseline HbA1c, low C-peptide values, preoperative use of insulin, long diabetes duration and low magnitude of weight loss have been negatively related to type 2 diabetes remission." (PMID 32283783, 2020). "Moderate alcohol consumption has been shown to increase insulin sensitivity, and to contributes to a lower risk of diabetes development in Japanese men." (PMID 31996224, 2020). "DEB is more common in females with T1DM and is frequently associated with insulin omission for weight control and consequent higher rates of diabetes-related medical complications and tripled risk of mortality." (PMID 33287458, 2020). "Dysregulated autophagy in pancreatic β cells due to hyperglycemia, oxidative stress, and inflammation is associated with diabetes and accompanied by dysregulated autophagy in insulin target tissues and the progression of diabetic complications." (PMID 33041786, 2020). "Previous data showed an association between relaxin, obesity, and diabetes, suggesting a role for the relaxin/insulin pathway in the development of metabolic disorders, including obesity." (PMID 32899471, 2020). "Long-term insulin was the primary therapeutic modality for diabetes, reflecting permanent loss in endocrine pancreatic function." (PMID 32733645, 2020). "The risk was highest for those exposed to insulin-treated pregestational diabetes, followed by non–insulin-treated type 2 diabetes and gestational diabetes." (PMID 32031649, 2020). "Proper OGLDs therapy and early insulin intensification with patient self-management education are essential for better outcomes and for reducing the risk of long-term complications of diabetes." (PMID 33081765, 2020). "ABCC8 and KCNJ11 control insulin secretion through the ATP sensitive potassium channel, polymorphisms in these genes are associated with diabetes." (PMID 33113859, 2020). "Trying to solve the problems associated with diabetes, different delivery systems using mesoporous silica as a substrate for the controlled release of insulin into the stream were developed." (PMID 32825791, 2020). "Diabetes is characterized by abnormal glucose metabolism, which is mainly manifested by a disorder or deficiency of insulin function." (PMID 32973635, 2020). "This type of diabetes is associated with insulin resistance and promotes gluconeogenesis despite high insulin levels." (PMID 33005004, 2020). "In multivariate regression analysis proximal optimization technique was associated with the lowest chance for restenosis (OR 0.15, 95% CI 0.06–0.33), whereas diabetes on insulin was associated with the highest risk of restenosis (OR 4.21, 95% CI 1.48–11.44)." (PMID 32411301, 2020). "Diabetes mellitus (DM) is a common endocrine disease of dogs characterized by an absolute or relative deficiency of insulin." (PMID 33124730, 2020). "In our previous report, we had demonstrated DPP-4 mediates the insulin resistance signals, leading to the pathological phenomenons associated with diabetes and its complications." (PMID 33267804, 2020). "In the univariable analysis, the identified risk factors for hypoglycemia were BMI, diabetes, eGFR < 60 ml/min/1.73 m2, insulin treatment, pre-treatment glucose, and location of treatment in ED." (PMID 33328554, 2020). "Increased fiber consumption is linked to improved insulin sensitivity and to lower hemoglobin A1c percentages in patients with diabetes and pre-diabetes." (PMID 32824428, 2020). "KK-Ay mice with the lethal yellow obese (Ay) mutation and develop diabetes of polygenic origin, showing severe obesity, hypertriglyceridemia, hyperglycemia, hyper-insulinemia, and insulin function loss by 42 weeks of age18,21,25,26." (PMID 32999320, 2020).
diabetes (continued). "Lifestyle interventions have been shown to have beneficial effects in terms of reduction in the risk of diabetes by increasing insulin sensitivity, weight loss as well as better glycemic and lipid control." (PMID 33235604, 2020). "Diabetes is characterized by rising levels of blood glucose and is often associated with a progressive loss of insulin-producing beta cells." (PMID 33158929, 2020). "Incidence and rates of hypoglycaemia were higher in TAKE CONTROL compared to ITAS, likely because of the greater hypoglycaemia risk (longer diabetes duration, antecedent insulin treatment in >60% of subjects, continued use of SU/glinides in TAKE CONTROL)." (PMID 32118347, 2020). "Other studies have shown that a single nucleotide polymorphism (SNP) of AHSG gene was associated with the prevalence of type 2 diabetes mellitus, and circulating fetuin-A concentration was negatively correlated with insulin secretion." (PMID 32134969, 2020). "Diabetes mellitus is a chronic disease that is characterized by an absolute or relative deficiency of insulin, the hormone that stimulates the transport of glucose across cell membranes, which leads to an increase in blood glucose—hyperglycemia." (PMID 32911736, 2020). "Diabetes is a chronic metabolic disease caused by an impairment of the hormone insulin which results in elevated blood glucose." (PMID 32467827, 2020). "According to our results, during prolonged periods of starvation, a reduction of IGF1R signaling would cause an increase in insulin granule release, which is observed in the physiopathology of diabetes." (PMID 32934005, 2020). "In congenitally leptin-deficient ob/ob mice, which have severe diabetes and metabolic dysfunction, adiponectin overexpression was able to reverse their phenotype, restoring normal glucose and insulin levels." (PMID 33133017, 2020). "Hyperglycemia is caused by a deficiency of insulin production by pancreatic (Type 1 diabetes mellitus) or the insufficiency of insulin production in the face of insulin resistance (Type 2 diabetes mellitus)." (PMID 32635546, 2020). "Diabetes mellitus is a metabolic disorder that majorly affects the endocrine gland, and it is symbolized by hyperglycemia and glucose intolerance owing to deficient insulin secretory responses and beta cell dysfunction." (PMID 32148647, 2020). "Diabetes mellitus is a group of metabolic disorders characterised by hyperglycemia and caused by defects in insulin production, insulin action or both." (PMID 32407347, 2020). "Genetic studies have shown that type 2 diabetes risk alleles, which have been shown to predispose to diabetes by reducing insulin secretion, were associated with reduced birth weight when inherited by the fetus." (PMID 33490284, 2020). "Intensive glucose control with metformin decreased the risk of diabetes-related endpoints in overweight diabetic patients, and was associated with less weight gain and fewer hypoglycemic attacks than are insulin and sulfonylureas." (PMID 32489427, 2020). "These agents are widely regarded as the most prominent cytotoxic diabetogenic glucose analogues for inducing experimental diabetes, while alloxan generates oxidative damage of insulin-producing β-cells, STZ causes DNA fragmentation and destroys the β-cells." (PMID 32244448, 2020). "Adiponectin is a major regulator of glucose metabolism with insulin-sensitizing properties; thus, low levels of adiponectin are associated with diabetes." (PMID 31905496, 2020). "The inability of β-pancreatic islet to produce sufficient insulin or un-utilization of insulin by the body is an underlining pathology of Diabetes mellitus." (PMID 32843013, 2020). "Diabetes mellitus (DM) is characterized by prolonged high blood glucose levels due to absolute or relative deficiency of insulin." (PMID 33553143, 2020). "Diabetes is divided into type 1 and type 2, which are characterized by insulin deficiency or the defective insulin response." (PMID 32722262, 2020).
diabetes (continued). "Severe diabetes caused ultrastructural changes in bone formation, and insulin therapy allowed an improvement in osseointegration, but it was not possible to reach the results obtained in the control group." (PMID 33331451, 2020). "Diabetes mellitus is a metabolic disease characterized by hyperglycemia, which is caused by insulin secretion defects or insulin dysfunction." (PMID 30736400, 2019). "Several circRNAs have been implicated in the pathological progression of diabetes, including reducing β-cell proliferation, reducing survival, and affecting insulin secretion." (PMID 31398847, 2019). "The identification of homozygous INS mutation in patient 7 refined the diagnosis of diabetes in her siblings, who was originally diagnosed with type 1 DM (T1DM) at first presentation." (PMID 31441606, 2019). "The major clinical risk factors for DR were duration of diabetes and receipt of insulin treatment, as have been identified in numerous studies, including those from India." (PMID 31070699, 2019). "Longer duration of diabetes and insulin-induced lipohyperthrophy were also associated with poor glycemic control." (PMID 31454396, 2019). "Diabetes is a chronic disease with serious metabolic disturbances in carbohydrate, protein and fat metabolism arising due to insulin deficiency or insulin dysfunction." (PMID 30733818, 2019). "Physical activity has also been associated with insulin sensitivity in Indonesia and reduced incidence of diabetes in prior studies." (PMID 31469876, 2019). "Diabetes mellitus is a group of metabolic diseases characterised by chronic high blood glucose levels, due to deficiency in insulin secretion, insulin action or both (World Health Organisation [WHO], 2016)." (PMID 34040849, 2019). "In obesity and diabetes, impaired ER stress termination signals, including the down-regulation of Sdf2l1 that is caused by decreased insulin signaling, sustains ER stress and exacerbates insulin resistance, creating a vicious cycle." (PMID 30814508, 2019). "Diabetes and insulin resistances have been reported to be independent risk factors for liver fibrosis and cirrhosis." (PMID 30680526, 2019). "This analysis also identified several critical pathways linked with diabetes pathophysiology, including calcium signaling, insulin secretion, insulin signaling, and TGF-β signaling." (PMID 31775218, 2019). "Insulin therapy is suggested for patients with T2DM being treated with oral hypoglycemic agents but who report poor glycemic control." (PMID 30807441, 2019). "Type 2 diabetes mellitus is reported to be the result of an impairment in insulin sensitivity and relative insulin deficiency." (PMID 31488172, 2019). "Diabetes mellitus (DM) is a complex and serious metabolic disease associated with abnormally high levels of blood glucose attributed to defective insulin secretion or action." (PMID 31885637, 2019). "In the male diabetes patients, in line with previous studies, showed that treatment with “oral agent and insulin injection” or “insulin injection” was more likely to cause depressive symptoms than treatment with “oral agent” alone." (PMID 31726788, 2019). "Diabetes mellitus (DM), in all its forms, is a metabolic disorder that occurs due to deficient production of insulin by the pancreas." (PMID 30820250, 2019). "Diabetes is a prevalent metabolic disease characterized by high blood sugar caused by either inadequate insulin production by beta cells in the pancreas, or by a defective response to insulin in the liver, muscle and adipose tissue." (PMID 31061237, 2019). "Diabetes mellitus, one of the most common metabolic disorders in the world, is featured by hyperglycemia caused by either decreased insulin secretion or insulin resistance." (PMID 31185622, 2019).
diabetes (continued). "Excessive visceral fat causes the release of free fatty acids into the circulation, insulin resistance, and secretion of inflammatory adipokines, thereby raising the risk of metabolic diseases such as diabetes and non-alcoholic fatty liver disease." (PMID 31514294, 2019). "Clinical and demographic characteristics, a frequency of use of each diabetes mellitus treatment type, and the association of insulin pen use with health outcomes are reported using descriptive analysis and propensity score modeling." (PMID 31461470, 2019). "As for classic T1DM, ICI-induced diabetes is also caused by a severe insulin deficiency with low or undetectable levels of C-peptide and require long-term insulin therapy." (PMID 31870373, 2019). "High fibre intakes have been consistently inversely associated with some obesity- and diabetes-related outcomes (i.e., BMI, body fat, fasting glucose, and fasting insulin), colon cancer, and cardiovascular disease." (PMID 31744179, 2019). "Close to diabetes onset, the unmethylated INS ratio was associated with mIAA (p = 0.003), ECL-IAA (p = 0.002), and IA2A (p = 0.01) levels, but not with GADA, ECL-GADA, ECL-IA2, or ZnT8A levels." (PMID 31398795, 2019). "Type 2 diabetes mellitus (T2DM) is a disease characterized by an impaired insulin action, and is considered one of the major causes for illness and premature death, which results from severe complications of the disease." (PMID 31234331, 2019). "We have recently shown that deletion of Sorcs1 in mice made obese with the leptinob mutation results in diabetes and an insulin granule stability defect." (PMID 31857633, 2019). "Type 1 diabetes mellitus (DOID:9744) is characterized by loss of the insulin-producing beta cells of the pancreatic islets, leading to insulin deficiency." (PMID 31760947, 2019). "To date, WAT browning has been described as a beneficial event in the context of obesity and diabetes, as it has been shown to promote weight loss and improve insulin sensitivity in both metabolic conditions." (PMID 31740668, 2019). "Omentin has been intimately linked with protective mechanisms against insulin-resistant states, for example, obesity and diabetes." (PMID 31803136, 2019). "Other types of secondary diabetes include diabetes associated with the diseases of the pancreas and the destruction of insulin-producing cells." (PMID 35919481, 2019). "Non-insulin-dependent diabetes mellitus (type 2 diabetes, DM) has become a serious health concern characterized by hyperglycemia due to inadequate production of insulin, causing complications such as cardiovascular diseases, retinopathy and nephropathy." (PMID 31071910, 2019). "A recent study on the relationship between different T2DM diabetes subgroups and outcomes showed that the severely insulin-deficient subgroup had the highest risk of retinopathy." (PMID 31485449, 2019). "Heavy alcohol consumption is a risk factor for diabetes, which is characterized by impaired insulin secretion and insulin resistance." (PMID 31882596, 2019). "Hypoglycemia is associated with an increased risk of cardiovascular events and all-cause mortality in insulin-treated patients with diabetes." (PMID 30781593, 2019). "The duration of diabetes prior to surgery, glycemic control, insulin use, age, and postoperative weight loss have previously been suggested as factors influencing the chance of achieving remission of T2D after bariatric surgery." (PMID 31747392, 2019). "Diabetes mellitus is a chronic metabolic syndrome with the characteristics of insulin resistance or hyperglycemia caused by absolute or relative insufficiency of insulin secretion and/or deficient function of islet β cells." (PMID 31139382, 2019). "In this study, a diabetes mice model with insulin secretion deficiency and insulin resistance induced by streptozotocin injection and high fat diet feeding was established to imitate hybrid diabetes in human." (PMID 30733818, 2019).